MIGA2 (mitoguardin 2)
Description:
Regulator of mitochondrial fusion: acts by forming homo- and heterodimers at the mitochondrial outer membrane and facilitating the formation of PLD6/MitoPLD dimers. May act by regulating phospholipid metabolism via PLD6/MitoPLD.
Synonyms: C9orf54; FAM73B; FLJ14596; FLJ00199
Tractability: Antibody: its Gene Ontology location is reachable by antibodies, with high confidence; UniProt predicts a signal peptide or a membrane-spanning region. PROTAC: ubiquitination databases record sites on it.
Gene: Protein-coding gene on chromosome 9 (129,036,614 to 129,072,087, forward strand). Ensembl gene ENSG00000148343.
Subcellular location: Mitochondrion outer membrane
Subcellular location (Human Protein Atlas): Cytosol; Cell Junctions
Pathways (Reactome):
Metabolism: Synthesis of PA
Gene Ontology:
Molecular function: protein binding; protein heterodimerization activity; protein homodimerization activity
Biological process: mitochondrial fusion
Cellular component: cytosol; mitochondrial outer membrane; mitochondrion; plasma membrane
Genetic constraint (gnomAD): Loss-of-function variants: 36 observed, 68.35 expected, observed/expected ratio (o/e) 0.53, 90% interval 0.4 to 0.7. The upper end of that interval is the gene's LOEUF score, 0.7, which puts it in group 2 of 6, group 1 being the genes least tolerant of losing a copy. Missense variants: 657 observed, 805.59 expected, observed/expected ratio (o/e) 0.82, 90% interval 0.76 to 0.87. Synonymous variants: 332 observed, 357.27 expected, observed/expected ratio (o/e) 0.93, 90% interval 0.85 to 1.02.
Homologues: Orthologues: chimpanzee MIGA2 (99% identical), macaque MIGA2 (97% identical), dog MIGA2 (93% identical), pig MIGA2 (93% identical), mouse Miga2 (93% identical), rat Miga2 (91% identical), guinea pig MIGA2 (90% identical), rabbit MIGA2 (79% identical), tropical clawed frog miga2 (71% identical), zebrafish miga2 (62% identical), Drosophila melanogaster Miga (30% identical), Caenorhabditis elegans miga-1 (24% identical). Paralogues in human: MIGA1 (39% identical).
Diseases named in the same sentence as MIGA2 in open-access papers:
MIGA2 is named in the same sentence as 12 diseases in open-access papers, as found by Europe PMC text mining. Sharing a sentence is not in itself a finding about the gene and the disease. The quoted sentences say what the papers report.
hyperandrogenism (1 paper, 2023). Excessive secretion of androgens from the adrenal glands or gonads. "In addition, YAP1 has been identified as a susceptibility gene for PCOS, and MIGA2 is associated with hyperandrogenism in PCOS." (PMID 38012141, 2023). "Since MIGA2 and YAP1 are associated with hyperandrogenism in PCOS, this study may provide new clues to the molecular pathogenesis of PCOS." (PMID 38012141, 2023). "MIGA1 or MIGA2 (MIGA1,-2) expression has been implicated in hyperandrogenism in patients with PCOS." (PMID 38012141, 2023).
influenza (1 paper, 2016). An acute viral infection of the respiratory tract, occurring in isolated cases, in epidemics, or in pandemics; it is caused by serologically different strains of viruses (influenzaviruses) designated A, B, and C, has a 3-day incubation period, and usually lasts for 3 to 10 days. "The influenza-specific mAbs CH65 IgG and mIgA2 were included as isotype-specific negative controls." (PMID 27919754, 2016).
tumor (2 papers, 2017 to 2025). "In contrast, elevated expression of the MIGA2 gene was linked to improved survival outcomes, indicating a potential correlation with favorable prognosis in tumor patients." (PMID 40510359, 2025).
infection (1 paper, 2016). The state of being infected such as from the introduction of a foreign agent such as serum, vaccine, antigenic substance or organism. "Similar to b12 IgG, the CD4bs bnAbs CH31 IgG, mIgA2 and dIgA2 also consistently blocked snLuc.HIV-1JR-CSF infection to undetectable levels." (PMID 27919754, 2016).
MIGA2 also shares sentences with these, for which no sentence is quoted: chronic pancreatitis (1 paper); fibrosarcoma (1); hyperlipidemia (1); melanoma (1); neurological disease (1); Obesity (1); osteoporosis (1); polycystic ovary syndrome (1).